LPL (lipoprotein lipase)
Diseases named in the same sentence as LPL in open-access papers (continued):
Sharing a sentence is not in itself a finding about the gene and the disease.
Obesity (continued). "However, there is no other detailed information about the anti-obesity property of the red skin from lotus seed, especially via regulating lipoprotein lipase activity." (PMID 35885328, 2022). "While LPL is increased in obesity its functional regulation is impaired, with recent evidence suggesting that increased APOC3 and ANGPTL3 in obese individuals may contribute to reduced LPL activity and reduced remnant particle clearance." (PMID 33193106, 2020). "This could suppress lipoprotein lipase activity which, in turn, could impair several aspects of lipid metabolism (such as triglycerides uptake and HDL production) and contribute to the development of obesity on the long term." (PMID 26872944, 2016). "Though not significant, suggestive AM associations included LPL and CYP4F22, which are associated with type 2 diabetes and lipid metabolism (rs1372339, rs4922116, rs1273516), and TMEM18 (rs2947411), associated with obesity and body mass index." (PMID 23424626, 2013). "The lack of LPL in beta cells of ob/ob mice could be due to the lack of leptin per se, or could be a consequence of obesity and/or the high levels of glucose, fatty acids and insulin in the blood." (PMID 23186339, 2012). "The down-regulation of LPL in the adipose tissues, muscles and kidney under study may be due to inflammatory mediators such as tumour necrosis factor-alpha (TNF-α) which are found to be elevated in obesity and insulin resistant states." (PMID 20670429, 2010). "Therefore, we rule out a role of LPL to explain increased obesity in apoCIII mice." (PMID 26705406, 2015). "We have also shown that while mice lacking pan-neuronal LPL develop obesity, this obesity is not exacerbated on an HF diet, or rescued by a PUFA enriched diet, further highlighting the importance of LPL in lipid sensing and body weight regulation." (PMID 28421037, 2017). "In this sense, the anti-obesity effects of Gambisan appear to be exerted, not by the lipolysis pathway related with HSL, but by the dose-dependent downregulation of LPL." (PMID 24069055, 2013). "Moreover, proteins responsible for transport of small molecules, namely chylomicron remodeling and assembly of active LPL and LIPC lipase complexes, were not enriched in control vs. obesity comparison." (PMID 38732002, 2024). "However, there is no information on the effect of obesity on the mammary gland gene expression of SCD1, LPL, CD36, and PPARG1." (PMID 38133242, 2023). "Finally, the detailed mechanism of how obesity promotes lipid accumulation in LNM and the role of LPL/CD36 in this process were not investigated." (PMID 36397145, 2022). "In addition, in female rats the administration of LPL inhibitor did not change retroperitoneal lipogenesis, suggesting that there is a specific sex-dependent response in the development of MSG-induced obesity." (PMID 30738429, 2019). "Cells isolated from elderly subjects with or without obesity were significantly impaired in their capacity to differentiate into adipocytes, as revealed by Oil Red O staining of neutral lipids and by the gene expression of common adipogenic markers (PPARG, FABP4, LPL, PLIN1, and FASN)." (PMID 35811457, 2022).
dyslipidemia (201 papers, 2006 to 2026). "Patients with chronic kidney disease face an elevated risk of developing dyslipidemia because of reduced activities of lipoprotein lipase and lecithin cholesterol acyltransferase, along with lower hepatic lipase levels." (PMID 40725745, 2025). "Different studies have reported sequence variants of the LPL gene locus across different populations, revealing novel and common variants associated with an increased risk of developing dyslipidemia and BMI." (PMID 40806414, 2025). "Elevated prolactin levels reduce lipoprotein lipase activity, which is associated with hypogonadism, weight gain, and dyslipidemia." (PMID 40650124, 2025). "The level of LPL in peripheral bloodstream tends to be lower in individuals with more risk factors for metabolic syndrome, such as impaired glucose tolerance, dyslipidemia, and hypertension." (PMID 41156460, 2025). "Metabolic syndrome components were modified following interaction between PvuII and HindIII, two main LPL polymorphisms, with carbohydrate intake in the KMSRI-Seoul Study14." (PMID 41372238, 2025). "The main mechanisms in DM causing dyslipidemia can be categorized into two types: increased activities of adipocyte and hepatic lipases and decreased activity of lipoprotein lipase (LPL)." (PMID 38892018, 2024). "Residents with excessive waistline are at increased risk of dyslipidemia due to excessive accumulation of abdominal fat, resulting in increased insulin resistance, decreased lipoprotein lipase activity, and increased TG and TC proteolipase activity." (PMID 39678246, 2024). "Previous studies demonstrated that abnormal lipoprotein lipase, including deficiency and mutation, was firmly associated with the incidence of dyslipidemia, leading to consequences such as atherosclerosis and stroke." (PMID 36551995, 2022). "This study indicated that individuals with dyslipidemia carrying rare synonymous variants within the LPL gene had an attenuated response to the fibrate therapy." (PMID 36551995, 2022). "Firstly, GALT2 directly regulates HDL metabolism of mammalian; secondly, GALT2 act as an inhibitor of ANGPTL3, which causes dyslipidemia; thirdly, LPL activity is controlled by ANGPTL3, and LPL is a key enzyme in lipid metabolism." (PMID 36618414, 2022). "In a previous study, a DMC in the LPL promoter was found in VAT from individuals with metabolic syndrome and was positively associated with a worse metabolic profile." (PMID 36535927, 2022). "The genetic association has been described for PvuII and S447X polymorphisms in the LPL gene with various pathological conditions, including dyslipidemia, hypertension, CVD, and T2D." (PMID 32887252, 2020). "The LPL inhibition increased the proportion of HDLsmall (HDL3a+3b+3c), which is related to the risk of metabolic syndrome." (PMID 31234537, 2019). "In contrast, it has been shown that decreased serum LPL concentrations are associated with metabolic syndrome, diabetes, and coronary atherosclerosis." (PMID 30947712, 2019). "List of 46 potential SNPs at the LPL gene locus for genetic association studies of dyslipidemia, the metabolic syndrome and coronary heart disease." (PMID 29438437, 2018). "It is strongly recommended that KUA LPL-27: g.18704C>A be investigated in other ethnic groups as well as to investigate its potential association with clinical manifestations of dyslipidemia such as diabetes mellitus and/or heart disease." (PMID 29438437, 2018). "Genetic studies have implicated several gene loci in the predisposition to dyslipidemia in Asian Indians, one of which is lipoprotein lipase (LPL)." (PMID 28115978, 2017). "Prevalence in the cohort of probands with atherogenic dyslipidemia of non-synonymous exonic variants in the LPL gene." (PMID 25897955, 2015). "Several studies showed that insulin affects the liver apolipoprotein production and regulates the enzymatic activity of lipoprotein lipase and cholesterol ester transport protein, which causes dyslipidemia in diabetes mellitus." (PMID 24918095, 2014).
dyslipidemia (continued). "It is well known that rare LPL mutations cause marked dyslipidemias (e.g., familial LPL deficiency with chylomicronemia, at least some of which are known to be involved in the development of premature atherosclerosis." (PMID 22837712, 2012). "Given that ox-LDL is closely associated with dyslipidemia and atherosclerosis, Cys-C could indirectly affect lipoprotein lipase activity or other enzymes that modify LDL particles, thereby influencing the balance between native and oxidized forms of LDL." (PMID 40243674, 2025). "Decreased LPL activity is closely associated with metabolic syndrome, a cluster of complex metabolic disorders that includes abdominal fat accumulation, elevated triglycerides, high cholesterol, hypertension, hyperglycemia, and non-alcoholic fatty liver disease." (PMID 40625358, 2025). "Further, an attenuation of angiopoietin-like 3 activity, an inhibitor of lipoprotein lipase (LPL), may be involved in the amelioration of the metabolic syndrome-associated dyslipidemia." (PMID 39596505, 2024). "Triacylglycerols deficiency results in reduced LPL activity and type V dyslipidemia." (PMID 38455763, 2024). "The potential benefits of dietary Mg supply on dyslipidemia management may be linked to the fact that Mg participates in the modulation of lipoprotein lipase (LPL), desaturase (DS), HMG-CoA reductase, and lecithin-cholesterol acyl transferase (LCAT) activity." (PMID 35565682, 2022). "Given the correlation in improvement in TRIG and HDL that we have found following bariatric surgery, LPL is a leading candidate as an FXR-mediated mechanism underlying the improvement in metabolic syndrome related dyslipidemia characterized by high TRIG and low HDL." (PMID 27006824, 2016). "A previous study speculated that the gene encoding LPL played an important role in dyslipidemia in an Asian population." (PMID 26786614, 2016). "Heterozygous LPL deficiency is more common as it is estimated to be present in 3–7% of the general population, and is known to be associated with a greater risk of dyslipidemia, metabolic syndrome and atherosclerosis." (PMID 26263173, 2015). "Furthermore, although it is known that dyslipidemia is associated with IR and T2D, information is limited on the association between LPL, 25(OH)D, IR and T2D in population studies." (PMID 23320821, 2013). "Also, in our previous study that evaluated 66 SLE patients, with exclusion causes of dyslipidemia, we found positive anti-LPL in 37.8% of them." (PMID 19606253, 2009). "Importantly, hereditary forms of dyslipidemia have been in part attributed to ablative mutations in LPL." (PMID 16822320, 2006). "Similarly, LPL variants that predispose to dyslipidemia could exacerbate neurovascular changes that contribute to depression." (PMID 41464486, 2025). "LPL deficiency or dysfunction can cause dyslipidemia, which may increase the risk of AD18." (PMID 34108502, 2021). "In addition, “common” genetic variants of certain gene locus such as LPL may contribute to the missing heritability value of dyslipidemia for different populations." (PMID 29438437, 2018). "Lipoprotein lipase gene mutations may play an important role in dyslipidemia in T2DM patients." (PMID 27115999, 2016). "Mainly present in genes of lipid metabolic pathways (APOA5, APOB, APOC3 and LPL), the higher frequency of risk alleles in Puerto Ricans has been associated previously in other populations with unfavorable lipid profile and insulin response, cardiovascular conditions and metabolic syndrome." (PMID 19682384, 2009). "Under streptozotocin (STZ)-induced diabetes, VegfbKO rats exhibited increased cardiac LPL activity, protecting animals from dyslipidemia, decreased plasma saturated FA, and provided a safer cardiac FA source, LPL-derived FA." (PMID 41788807, 2026). "Up to 90% of hypothyroid patients exhibit dyslipidemia characterized by elevated triglycerides due to increasedhepatic fatty acid esterification and reduced lipoprotein lipase activity." (PMID 41393433, 2025).
dyslipidemia (continued). "Dysregulation of LPL activity can lead to atherogenic dyslipidemia, characterized by elevated TG and reduced HDL-C levels, which are hallmark features of metabolic syndrome and associated with increased cardiovascular risk." (PMID 40077646, 2025). "Lipoprotein lipase (LPL) is identified as a key enzyme for lipid metabolism, and its abnormal levels are significantly associated with metabolic syndrome, diabetes, and cardiovascular diseases." (PMID 41372238, 2025). "CKD, which is correlated with dyslipidemia, results in the downregulation of lipoprotein lipase and the LDL-receptor as well as delayed metabolism and the clearance of triglyceride-rich lipoprotein and lipids, elevating lipid (cholesterol, LDL, and TG) levels." (PMID 38921435, 2024). "Briefly, WAT A4 primarily functions as an autocrine regulator of LPL during fasting by inhibiting LPL activity and promoting its degradation, and targeting A4 emerges as a promising therapeutic approach for managing dyslipidemia and cardiovascular diseases." (PMID 38521668, 2024). "P-407 induces dyslipidemia by promoting cholesterologenesis and suppressing TG hydrolysis via LPL inhibition." (PMID 39458984, 2024). "High TG levels, the hallmark of CKD-induced dyslipidemia, are caused by increased hepatic production of VLDL accompanied by diminished catabolism by lipoprotein lipase and hepatic lipase." (PMID 38720111, 2024). "Plasma LPL activity was reduced in rats with dyslipidemia (p < 0.001), and that effect was reversed dose-dependently by ARB." (PMID 39458984, 2024). "It promotes dyslipidemia through various mechanisms, including the decreased activity of key enzymes such as lipoprotein lipase (LPL)." (PMID 39457689, 2024). "Both behaviors contribute for example to dyslipidemia by inhibiting lipoprotein lipase activity, leading to higher triglyceride levels and lower HDL-cholesterol, thus increasing the risk of cardiovascular events and mortality." (PMID 39472875, 2024). "Dyslipidemia can occur when LPL malfunctions leading to hypertriacylglycerolemia (hypertriglyceridemia, chylomicronemia), an independent risk factor for CVD due to plasma accumulation of chylomicrons and very low-density lipoproteins (VLDL)." (PMID 38455763, 2024). "One gene that has been implicated in metabolic syndrome is the LPL gene, which encodes for lipoprotein lipase, an enzyme involved in the metabolism of lipids." (PMID 38429792, 2024). "The impairment of a rate-limiting FA oxidation enzyme, carnitine palmitoyltransferase 1 (CPT1), and a rate-limiting TG hydrolysis enzyme, lipoprotein lipase (LPL), is also important mechanism in the development of hepatic lipid accumulation and dyslipidemia." (PMID 36615905, 2023). "Angiopoietin-like protein (ANGPTL) complexes 3/8 and 4/8 are established inhibitors of LPL and novel therapeutic targets for dyslipidemia." (PMID 38160757, 2023). "It was observed that decreased LPL expression seems to induce dyslipidemia as ApoE−/− mice had reduced levels of HDL-C and elevated levels of TAG as well as CHOL." (PMID 35883883, 2022). "In CIH disease models, HIF-1 promotes Angptl4-mediated dyslipidemia and upregulates the expression of Angptl4, which, in turn, inhibits LPL activity and catalytic function, resulting in hyperlipidemia." (PMID 36285165, 2022). "Lipoprotein lipase (LPL) plays a crucial role in preventing dyslipidemia by hydrolyzing triglycerides (TGs) in packaged lipoproteins." (PMID 35911520, 2022). "This study provides evidence that rs117026536 of the LPL gene is related to the occurrence of dyslipidemia in the Korean population." (PMID 36419087, 2022). "As a result, the LPL activity is inhibited, preventing lipid uptake into peripheral tissues from the circulating lipoproteins, potentially contributing to dyslipidemia." (PMID 36292250, 2022). "Meanwhile, for the formation of LDL, an important parameter in dyslipidemia is mediated by lipoprotein lipase (LPL) in muscles and adipose tissues." (PMID 36551995, 2022).
dyslipidemia (continued). "As the main regulator of Angptl4, HIF-1 plays a role in promoting arteriosclerosis and dyslipidemia by upregulating Angptl4, inhibiting the expression of LPL, and increasing triglycerides and lipids in CIH-induced lipid metabolism and arteriosclerosis." (PMID 36285165, 2022). "In the current study, we found that CIH exposure aggravated dyslipidemia in ApoE−/− mice, but that DLT treatment effectively improved the dyslipidemia and alleviated the decrease in LPL activity caused by hypoxia." (PMID 36285165, 2022). "Increased plasma LPL activity has been detected in ASD and an analysis of dyslipidemia in ASD identified sex-differentially expressed, neurodevelopmentally co-regulated, ASD segregating deleterious variants of LPL." (PMID 34504056, 2021). "LPL-mediated TG hydrolysis is the rate-limiting step for FFA transfer into adipose and other tissues, and impairment of LPL-mediated lipolysis is one of the possible pathogenetic mechanisms leading to dyslipidemia in the obese population." (PMID 34436472, 2021). "In fact, inflammatory cytokines like IL-6 were shown to link with dyslipidemia by promoting de novo hepatic fatty acid synthesis and suppressing the activity of lipoprotein lipase, a key enzyme involving in catabolism of triglyceride-rich lipoproteins." (PMID 34208976, 2021). "Metabolism of VLDL in peripheral tissues is dependent on endothelial lipoprotein lipase, which has been shown to have reduced activity by insulin in metabolic syndrome." (PMID 34745660, 2021). "Studies have found that in obesity, there is impaired LPL activity and lipolysis, reducing the removal of postprandial FFAs and contributing to dyslipidemia through upregulated hepatic VLDL release which increases TG levels." (PMID 34436472, 2021). "VDD zebrafish exhibited elevated hepatic triglycerides, attenuated plasma free fatty acids and attenuated lipoprotein lipase activity consistent with hallmarks of dyslipidemia." (PMID 32994480, 2020). "Previous studies have shown that GA offsets the development of visceral obesity and improves dyslipidemia by selectively inducing the expression of tissue lipoprotein lipase (LPL)." (PMID 30871060, 2019). "Accordingly, the protective effect of HDLlarge (HDL2a+2b) against metabolic syndrome was attenuated by LPL inhibition, strengthening the effect of HDLsmall (HDL3a+3b+3c) on metabolic complications." (PMID 31234537, 2019). "This relationship can be explained at least in part by its function in the inhibition the activity of lipoprotein lipase and stimulates adipose tissue lipolysis and relates to dyslipidemia." (PMID 31164103, 2019). "Dysregulation of lipoprotein lipase (LPL) contributes to dyslipidemia, and LPL inducers, such as PPAR ligands, NO-1886, and indomethacin, have been shown to decrease TG levels and suppress tumor development in animal models." (PMID 28505114, 2017). "Decreased activity of lipoprotein lipase (LPL) and slow catabolism of triglyceride-rich lipoprotein particles contribute to the development of dyslipidemia in patients with renal insufficiency." (PMID 27127544, 2016). "As the occurrence of dyslipidemia depends on factors such as insulin action on peripheral tissues and liver, apoprotein production and regulation of lipoprotein lipase, the duration of diabetes seems to play only a minor role in modifying these factors." (PMID 24918095, 2014). "On the other hand, it has been reported that patients with poorly controlled diabetes frequently have dyslipidemia due to defects in LPL enzyme activity." (PMID 22028972, 2012). "Dysfunction of LPL has been indicated in several disorders including dyslipidemia and atherosclerosis." (PMID 23110339, 2012). "The contribution of lipoprotein lipase (LPL) in the development of dyslipidemia and atherosclerosis is increasingly recognized." (PMID 16822320, 2006). "This dyslipidemia may be mediated by inflammatory cytokines (particularly TNF-α) through suppression of lipoprotein lipase (LPL) activity." (PMID 41508030, 2026).